IL1B (interleukin 1 beta)
Diseases named in the same sentence as IL1B in open-access papers (continued):
Sharing a sentence is not in itself a finding about the gene and the disease.
infection (continued). "While IL-1β release from ΔexoST infected neutrophils is also NLRC4-dependent, infection with PAO1 is instead NLRP3-dependent and driven by the ADP ribosyl transferase activity of ExoS." (PMID 37730693, 2023). "As in the experiments above, our data shows that cells infected with exosome-free L. braziliensis produced significantly less IL-1β, TNF, IL-10 and IL-6 upon infection." (PMID 37841240, 2023). "IL-1β, IL-12 (p40), IL-4, and CCL3 levels were modulated, showing significantly lower induction during early infection (1–9 hrs) followed by a significant increased after 12hrs." (PMID 37790429, 2023). "Upon ∆yopM infection, PS205 pyrin was maintained, and there was a significant decrease in IL-1β secretion with both siRNA combinations tested (respectively)." (PMID 37787552, 2023). "ELISA results showed decreased levels of inflammatory cytokines IL-6, IL-1β, and TNF-α at each infection time point." (PMID 38076459, 2023). "Elevated expression of multiple inflammatory genes, including IL6, TNF, IL10, and IL1B, were observed in the CD163+MRC1+TREM2 Mac and CD163+MRC1− subsets in both Cohort 1 and 2 after infection." (PMID 37024448, 2023). "IAVTNF-α demonstrated significantly higher levels of IL-6, IL-1β, IL-8, IFN-γ, and TNF-α in comparison to IAVQUI after 24 h infection." (PMID 37163429, 2023). "Pro-inflammatory cytokines (PICs) are activated following an infection, such as tumour necrosis factor-alpha (TNF-α), interleukin-1 beta (IL-1β), and IL-6." (PMID 36823611, 2023). "Infection of HKDM with both WT and ΔeseN E. ictaluri induces production of pro-IL-1β, but maturation of pro-IL-1β into IL-1β is inhibited." (PMID 37796003, 2023). "The increased secretion of IL-1β and concomitant activation of NLRP3 has also been observed upon infection with tissue and blood parasites." (PMID 37375100, 2023). "Vero E6 cells were pretreated with IFN-γ and/or IL-1β, then infected with SARS-CoV-2-mNG and stained with iNOS antibodies at 24 h post-infection for detection by laser scanning confocal microscopy." (PMID 38162653, 2023). "Infection with these bacteria induced solid inflammatory responses and a substantial increase in the inflammatory cytokine release of TNF‐α, IL‐6, IL‐1β, and IL‐18 in macrophages derived from March5fl/fl mice." (PMID 37575012, 2023). "Infections can disrupt the balance of cytokines (TNF-α and IL-1β), serum proteins, and white blood cell functions, all leading to inflammation and disease progression." (PMID 37569767, 2023). "Increased expression of several cytokine/chemokine genes was observed in MC-HBOs after infection of ZIKA (IL6, IL1β, TNFα, and CCL2) and Dengue virus (IL1β and CCL2)." (PMID 36474001, 2023). "The mRNA expression of pro-inflammatory cytokines, including IL-1β, IL-6 and TNF-α were significantly higher in the infection group than that in the control and nisin group (P < 0.05)." (PMID 37803465, 2023). "Infection with Aa elevates serum and intramural levels of TH17 cell-related factors, such as IL-1β, IL-17, IL-6, TGF-β, and IL-1β, indicating a potential induction of TH17 activation and the promotion of vascular inflammation." (PMID 37629042, 2023). "The levels of TNF-α, IL-1β, and IFN-γ were first elevated after infection and then returned to baseline at 14 dpi after the peak." (PMID 37920268, 2023). "From 7 to 14 dpi, the HuN4 infection group exhibited higher levels of IL-1β, whereas the SD53-1603 infection group displayed higher levels of TNF-α and IFN-γ." (PMID 37920268, 2023). "We also evaluated the levels of four proinflammatory factors (TNF-α, IL-6, IL-1β and IFN-γ) in THP-1 macrophages preincubated with chloroquine (20 μM) or rapamycin (5 μM), followed by infection with Mel+ or Mel˗ S. globosa conidia to activate autophagy." (PMID 37141335, 2023).
infection (continued). "The HLA-A11/DR1 mice strain induced lower levels of several cytokines (IL-2, IL-10, IL-18, IL-1β, TNF-α, IL-1α, IL-28, and ENA78), but showed increased secretion of IFN-γ, RANTES, IP10, and Eotaxin at 12 h post-infection, compared to the WT group." (PMID 38035330, 2023). "At 6 h post-infection, OMA- and NSC-treated cells had an inhibitory effect on IL-1β, IL-6 and IL-8, while BARM inhibited IL-6 and IL-8 levels." (PMID 36992362, 2023). "IL-1β, IL-6, and TNF-α mRNA expressions were significantly induced 12 h after infection with B1033, and when complemented with fadD33, these mRNA expressions reverted to those observed in the wild-type BCG strain." (PMID 37998345, 2023). "Infections with virulent ASFV isolates often results in increased levels of serum pro-inflammatory cytokines such as IL-1α and IL-1β." (PMID 36680273, 2023). "During the early phase of UPEC infection, the host cells release different factors, such as cytokines and chemokines (IL-1β, IL-6, IL-8 and TNF-α) and hormones (norepinephrine, estradiol), to fight off the infection." (PMID 37759520, 2023). "We found that TMAO aggravated the release of several key cytokines (IL-1β and IL-6) and chemokines (IL-8, CXCL1 and CXCL6) from bladder epithelial cells during a CFT073 infection." (PMID 37111409, 2023). "ALKBH5 knockdown increased the levels of the IL-1β, CSF3, TGM2, and SRC transcripts during infection by P. aeruginosa, C. diphtheriae, WT HSV-1, or the ICP34.5 mutant virus." (PMID 36625590, 2023). "IL-1β induces NOS2 and NO production and resistance to infection in C57BL/6 BMDM infected with L. amazonensis, and transcriptome data showed downregulation of Il1b in L. amazonensis infected BALB/c-BMDM." (PMID 37000792, 2023). "The signaling of IL‐1β mediated by NLRP3 inflammasome can also recruit NEs for virus clearance and host survival in IV infection." (PMID 37773712, 2023). "At the stage of severe infection and inflammation, macrophages first polarized to M1 phenotype by producing TNF-α, IL-1β, IL-12, and IL-23 against the stimulus l." (PMID 37065141, 2023). "Infection with both ZIKV lineages was characterized by a more proinflammatory and chemotactic profile, mediated by high levels of IL-1β, IL-6, TNF-α, CCL-2, CCL-3, CCL-7, CXCL8, IP-10, and VEGF." (PMID 37227282, 2023). "At the earlier stages of infection, MLKL-mediated necroptosis drives inflammasome activation, contributing to the maturation of IL-1β." (PMID 36852999, 2023). "In general, infection and disease induce fever, a physiological defensive response mediated by cytokines, such as TNF-α, IL-1β, and IL-6." (PMID 37621534, 2023). "For instance, activated NF-κB translocates to the nucleus, stimulating the secretion of inflammatory factors such as IL-1β, TNF-α, and IL-6, thus aggravating the inflammatory response after infection." (PMID 36979335, 2023). "Other serum cytokines measured were either unchanged during infection (CCL2) or below the limit of detection (IL-4, IL-1β and IL-10)." (PMID 37837930, 2023). "In contrast, infection with both VSV-g pseudotyped and replication competent HIV-1LAI induced IL-1β secretion and cell death only in CARD8 KO THP-1 cells that were complemented with WT human CARD8, but not CARD8 mutants that are resistant to HIV-1PR cleavage." (PMID 37417868, 2023). "HPV16 E6/E7 can obstruct the production of IL‐1β by inhibiting the binding of IRF6 on the IL‐1β promoter, which is critical in host defenses against injury and infection." (PMID 37719443, 2023). "Infection with Mon601 induced production of TNF-α and IL-1β RNA, and the EHI0578Y05 strain also stimulated expression of TNF-α RNA." (PMID 37515098, 2023). "The results showed a significant increase in both mRNA and protein levels of IL-6, IL-1β, and TNF-α in PBMCs and THP-1 cells after SFTSV infection." (PMID 36569095, 2022). "Other pro-inflammatory cytokines such as IL-1β, IL-6, and TNF-α are regulators of host responses to infection and positive mediators of inflammation." (PMID 36320076, 2022).
infection (continued). "Infection of primary human skin fibroblasts with CHIKV triggers, in addition to IFN-γ, increased expression of interleukin-1β (IL-1β), caspase-1 maturation, and expression of AIM2 inflammasome sensor." (PMID 36189282, 2022). "Prior to infection, the macrophages were either untreated or were primed with INF-γ, which can suppress the production of active IL-1β by macrophages." (PMID 36374090, 2022). "At 3 and 6 h post-infection, OMS-treated BMDMs and PMs had significantly higher mRNA levels of Tnf, Il1b, and Il12p40 compared to untreated controls." (PMID 36271707, 2022). "Although APPs are predominantly expressed by hepatocytes to be secreted into the blood, they can also be produced by endothelial cells and leukocytes activated by pro-inflammatory cytokines (e.g., IL1B and IL6) at the site of infection." (PMID 35401509, 2022). "Mean concentrations of IL-6, IL-1β, and TNF-α pre infection were 0.69 ± 0.27 pg/mL, 0.07 ± 0.03 pg/mL, and 0.32 ± 0.06 pg/mL (mean ± SE), respectively." (PMID 35281029, 2022). "This antigen-specific antibody-mediated infection was selectively coupled to chemokine ligand 5 (CCL5), interleukin 1β (IL-1β), and C-X-C motif chemokine ligand 10 (CXCL10) secretion and a reduction in granzyme B (GrB) release." (PMID 35862953, 2022). "There is increased release of the cytokines TNF, IL-1a, IL-1β, IL-2, and IFN-γ, as well as the recruitment of virus-specific T- and B-lymphocytes, accompanied by cellular and humoral antibodies to resist the infection." (PMID 35479306, 2022). "We found that the serum concentrations of TNF-α and IFN-γ were significantly increased after NE infection when compared to the CON group, although a similar IL-1β concentration was observed." (PMID 35387091, 2022). "To examine IL-6, IL-1β, IFN-γ, and TNF-α mRNA expression in mice lungs following infection with EHV-8, we inoculated BALB/c mice with EHV-8 and analyzed them by qPCR." (PMID 36230234, 2022). "With increasing severity of the infection, higher levels of circulating cytokines and other inflammatory biomarkers like IL6, IL-1β, TNFα, C-reactive protein (CRP) and D-dimer occurs." (PMID 36590303, 2022). "Following unisexual infection, the gene expression of the Th1 cytokines IFN-γ, IL-1β, IL-6 was upregulated in both the male-infected and female-infected groups compared to naive mice." (PMID 36505463, 2022). "SARS-CoV-2 infection also resulted in many cytokines and chemokines above baseline levels (all P < 0.05) throughout the infection, including IFN-γ, IL-1β, IL-4, IL-28, CXCL10, GM-CSF, LIF, CCL2, CCL7, MIP-1α, MIP-1β, RANTES, IFN-α, and IFN-β." (PMID 35634338, 2022). "On Day 7 post-infection with E. tenella, the levels of the components of the ChTLR15/NLRP3/IL-1β pathway in the caeca were again quantified, and the anticoccidial effects were assessed." (PMID 35303923, 2022). "Another study showed that F. nucleatum significantly promoted the secretion of TNF-α and IL-1β, while S. gordonii promoted the secretion of TNF-α, IL-6, IL-8, and IL-1β after 24 h of infection." (PMID 35573793, 2022). "This regulates the movement of proinflammatory cytokines (IL-1, IL-1β, and TGF-α), which increases the infection rate of the region and dysregulates the T-cells’ maturation." (PMID 36365254, 2022). "The mRNA expression level of IL-1β and TNFα has shown an increasing trend in Rag2−/− mice following SARS-CoV-2 MA10 infection." (PMID 36680154, 2022). "Human neutrophils also produce numerous different pro- and anti-inflammatory cytokines upon stimulation, such as TNF-α, IL-1β, IL-6 and IFN-γ, as well as a wide array of chemokines to recruit other immune cells to the site of infection." (PMID 36203565, 2022). "Restoration of LCN2 via transfection or infection, as well as addition of rhLCN2 in LCN2-KO#1 cells, showed the presumed upregulation of IL-1β." (PMID 35053376, 2022).
infection (continued). "Simultaneously, the protein levels of the inflammatory factors, including IL-1β, IL-6, and IL-8, were upregulated comparing the ASFV-infected to uninfected with infection time." (PMID 36311798, 2022). "Similar to the mtDNA levels, the levels of PICs (IL-6, IL-1β, and TNF-α) and IL-10 were consistently downregulated in patients with OmicronS infection." (PMID 36230930, 2022). "The concentration of cytokines in NHBE cells in response to infection in our study indicated that the expression of the proinflammatory cytokines IL-1β, IL-6, and TNF-α was induced by H7N9 infection, but reduced by pdmH1N1 in the early stage of infection." (PMID 35269402, 2022). "The results show that the secretion levels of IL-1β and IL-6 from the BALF and serum of Nlrp6−/− mice were significantly lower than those of WT mice after infection, while the secretion levels of TNF-α did not change." (PMID 36224650, 2022). "After infection with SARS-COV-2, the innate immune system is triggered, and various inflammatory pathways are activated, among which NLRP/IL-1β, JAK/STAT, TNF-α/NF-κB, and other pathways have been confirmed to be closely related to SARS-CoV-2 infection." (PMID 36278166, 2022). "denticola infections decreased IL-6, IL-1β, and CCL5/RANTES compared to single species infections with each of the bacterium in macrophage/epithelial cell co-culture model." (PMID 35203495, 2022). "Both IL-1α and IL-1β induce local inflammation and the recruitment and activation of neutrophils, monocytes and macrophages, which might act as a double-edged sword, limiting on infection the one hand and activating inflammation-related local and systemic damage on the other." (PMID 36551320, 2022). "Importantly, IL-1β release was entirely dependent on NLRC4 upon infection with any of these different Pseudomonas aeruginosa strains, whereas the pyroptotic strains PAO1ΔExoS, CHAΔExoS and PP34ΔExoU triggered neutrophil lysis and IL-1β release that was fully NLRC4-dependent." (PMID 35849616, 2022). "In contrast, later during infection, NLRP3 activation and production of IL-1β contributes to the induction of the cytokine storm and severe immunopathology." (PMID 36580480, 2022). "We found that pre-exposure to PS-NH2 significantly reduced mpo, il8, and irf3 transcription upon infection compared with NP-unexposed but NNV-infected cells, while exposure to PS-COOH decreased and increased that of mpo and il1b, respectively." (PMID 35163406, 2022). "Bacteria burdens, neutrophil recruitment, and activation (CD11b expression, myeloperoxidase, and elastase levels), interleukin (IL)-1β, IL-6, and tumor necrosis factor (TNF) were measured in bronchoalveolar lavage fluid (BALF) at 6 and 24 h after infection." (PMID 35269409, 2022). "ELISA indicated that the levels of the serum cytokines TNF-α, IL-1β, IFN-γ, IFN-β and IL-6 in chickens were significantly higher at 7 dpi after infection with IBV than in the control." (PMID 35909955, 2022). "IL-6, IL-8, IL-1β, TNF-α, and IFN-γ are pro-inflammatory cytokines involved in promoting the acute inflammatory response and defending against infection." (PMID 36364088, 2022). "For instance, infection of mouse bone marrow-derived macrophages (BMDM) with H. pylori stimulates the production of interleukin-6 (IL-6) and IL-1β via TLR2, IL-12, and IL-10 through the TLR4 pathways." (PMID 36317079, 2022). "Infection with both bacteria and DP1 antagonists significantly reduced the mRNA expression and secretion levels of IL-6, IL-1β, and TNF-α compared with those in the bacteria-only group (P < 0.05)." (PMID 36435808, 2022). "A recent study has also demonstrated that PA infection results in the activation of NLRP3 inflammasome in mice lungs, as indicated by induction of NLRP3 and ASC as well as caspase-1 and IL-1β." (PMID 36463179, 2022).
infection (continued). "Consistent with this, after AH1 infection, the levels of interleukin-6 (IL-6), tumor necrosis factor-alpha (TNF-α) and interleukin-1β (IL-1β) significantly increased in the lung tissues of p21˗/˗ mice compared with WT mice." (PMID 35180274, 2022). "We also found that KSHV de novo infection of primary endothelial cells increased the levels of IL1 signaling molecules, such as IL1β, IL1R1, IL1RAP, IL36α and IL36γ." (PMID 36457850, 2022). "Cytokines including IL-1β, IL-6, IL-12 p40, IP-10, IFN-γ, and TNF-α were increased in S. enteritidis-infected mice at 4 days post-infection." (PMID 35222370, 2022). "The results manifest that the mRNA levels of pro-inflammatory cytokines (IL-1β, IL-6, and TNF-α) in the PBS group increased significantly after infection." (PMID 35123452, 2022). "As the infection time of F. nucleatum increased, the expression levels of TNF-α and IL-1β also increased." (PMID 35765030, 2022). "BALF levels of the proinflammatory cytokines IL-1β, IL-6, and TNF were similar in both mouse strains at 6 h after infection." (PMID 35269409, 2022). "The infection with Pa increased NAG and MPO activities (indicative for macrophages and neutrophils, respectively) and the concentrations of CXCL-1, IL-1β, IFN-γ, and IL-10 compared to the NI group." (PMID 35548467, 2022). "vaccination resulted in significantly lower levels of evaluated proinflammatory cytokines, including IL-6, IP10, IL-1β, MCP-1, and IFN-γ in the lungs of infected mice at day 4 after infection, presumably due to the substantially reduced virus replication." (PMID 35446790, 2022). "During the early phase of infection (days 1–3 post-infection (p.i.)), the transcription of proinflammatory factors (i.e., IL-12, IFN-γ, TNF-α, IL-1β, IL-6, IL-18) was induced faster under BaP exposure." (PMID 35203386, 2022). "There was a significant increase in IL-1β and IL-8 mRNA expression levels of PAMs incubated with ASFV only with an increase in infection time from 3 to 12 h." (PMID 35215890, 2022). "The RANTES, IFN-α, MIP-1-α, and IFN-γ mRNA levels during reinfection were similar to the levels in the primary infection group; the levels of IL-6, IP-10, TNF-α, and IL-1-β were increased during reinfection but were lower than those during primary infection." (PMID 35893674, 2022). "Lastly, in response to M. bovis intramammary infection over a period of several days, initial elevations of TNF-α, IL-1β, and IFN-γ were observed between 90 and 102 h post infection, suggesting the late onset of these factors depend on causative pathogens." (PMID 35335696, 2022). "The expressions of IL-1β, IL-6, TNF-α, IFN-γ, IL-12, and CXCLi1 were also markedly increased in the livers of wild-type infected chickens on 5 days post-infection." (PMID 35694286, 2022). "Western blotting analyses uncovered that the cleavages of IL-1β (p17) and GSDMD (N-GSDMD) in the supernatants, and the production of pro-IL-1β in the cell lysates were induced by ECHO 11 infection." (PMID 36026486, 2022). "Expression levels of IL-1β, RANTES (CCL5), IP-10, eotaxin (CCL11), KC, MCP-1, MIP-2, and MIG were significantly lower in MET + PCV vs. control + PCV group at 7 days post-infection (all p < 0.05)." (PMID 35821804, 2022). "Next, we evaluated the presence of soluble polypeptides for IFNγ, IL-1β, IL-4, IL-6, IL-8, IL-10, CXCL10, and TNFα in serum of animals following infections with Att-S74-T3Bo and Vir-S74-T3Bo." (PMID 36466866, 2022). "In the acute phase of an infection, plasma levels of the inflammatory cytokines TNF-α, IL-1β and IL-6 increase, followed by enhanced secretion of acute-phase proteins that contribute to antimicrobial defence." (PMID 36510325, 2022). "In the case of SARS-CoV-2, an increase in the concentration of inflammatory cytokines such as IL-1β, IL-2, IL-6, IL-7 and TNF-α comes to the fore, along with the rise in IL-4 and IL-10 concentrations in a later stage of infection." (PMID 36294388, 2022).